EGFR (epidermal growth factor receptor)
Diseases named in the same sentence as EGFR in open-access papers (continued):
Sharing a sentence is not in itself a finding about the gene and the disease.
lung adenocarcinoma (continued). "Brain metastasis significantly contributes to the failure of targeted therapy in patients with epidermal growth factor receptor (EGFR)-mutated lung adenocarcinoma (LUAD)." (PMID 40069781, 2025). "This study compares the long-term survival of patients with stage IV lung adenocarcinoma treated with current therapies (checkpoint inhibitors or osimertinib for EGFR mutations) versus older treatments." (PMID 40227775, 2025). "Many lung adenocarcinomas have an actionable driver mutations involving genes such as epidermal growth factor receptor (EGFR), anaplastic lymphoma kinase (ALK), Kirsten rat sarcoma virus (KRAS), MET, c-ros oncogene 1 (ROS1), HER2, BRAF, RET, and NTRK." (PMID 40006675, 2025). "The clinical data of 187 individuals with stages IIIB–IV EGFR-mutated lung adenocarcinoma from Anhui Chest Hospital, collected from June 2017 to December 2023, were retrospectively analyzed." (PMID 41268168, 2025). "As of December 30, 2024, a total of 82 patients with advanced EGFR‐mutated lung adenocarcinoma were enrolled." (PMID 41399957, 2025). "Epidermal growth factor receptor (EGFR) mutations are the most common driver mutations found in patients with lung adenocarcinomas and occasionally found in squamous cell carcinomas." (PMID 39996857, 2025). "Patients with lung adenocarcinoma who have an EGFR mutation are treated with EGFR-TKIs, such as erlotinib and gefitinib, as their first line of treatment." (PMID 40728967, 2025). "Consistently, in our study, lung adenocarcinoma with acinar and papillary subtype had a higher EGFR mutation rate than solid and lepidic subtype." (PMID 40182027, 2025). "The results indicated that BS, PIS, VBS, MND, NV, ACTV, and SCP were associated with EGFR mutation in GGO-associated lung adenocarcinoma." (PMID 41020204, 2025). "Assessing EGFR mutations in lung adenocarcinoma demands rapid, accurate and cost-effective tests that preserve tissue for genomic sequencing." (PMID 40634781, 2025). "The advent of third-generation tyrosine kinase inhibitors (TKIs) has significantly improved the management of EGFR-mutated (EGFRm) lung adenocarcinoma (LUAD), establishing these inhibitors as the standard of care for first-line treatment." (PMID 40149368, 2025). "Specifically, the postoperative pathological stage of lung adenocarcinoma was pT1N2M0 with an EGFR exon 19 deletion mutation, while the prostate cancer was complicated by multiple metastases to the lungs, lymph nodes, and bones." (PMID 41426316, 2025). "A 52-year-old Chinese female patient with advanced lung adenocarcinoma harboring an EGFR Exon 19 deletion mutation presented with metastases to the bilateral lungs, brain, and right adrenal gland." (PMID 40428273, 2025). "Here, we present a case characterized by knee joint pain, ultimately confirmed through comprehensive investigations to be solitary fibular metastasis from lung adenocarcinoma with EGFR exon 19 deletion mutation." (PMID 39902235, 2025). "In lung adenocarcinoma patients with EGFR mutations or ALK rearrangements, first‐line targeted therapy is a routine treatment." (PMID 40347011, 2025). "This case underscores the diagnostic and therapeutic challenges of coexistent TB and EGFR-mutated lung adenocarcinoma." (PMID 41141063, 2025). "In this study, we assessed the role of AI-based radiomics and DL models using pre-treatment CT images of patients with lung adenocarcinoma to predict the EGFR mutation status." (PMID 38539465, 2024). "Lung adenocarcinoma carries an EGFR exon 20, HER2 insertion mutation in 2%, for which the first targeted therapy is trastuzumab deruxtecan, in patients already treated with platinum-based chemotherapy." (PMID 38605928, 2024). "Distribution frequency of MALAT1 genotypes of patients with lung adenocarcinoma and multiple logistic regression analysis of EGFR mutation association." (PMID 38517388, 2024).
lung adenocarcinoma (continued). "The present study aimed to identify early transcriptomic alterations associated with the DTP state in EGFR-mutated lung adenocarcinoma cell lines after a single exposure to TKIs." (PMID 39001552, 2024). "Three months ago, she was diagnosed with lung adenocarcinoma harboring an EGFR exon 21 p.L858R mutation." (PMID 39267801, 2024). "EGFR mutation is the most common genetic alteration in East Asian lung adenocarcinoma patients; hence, the survival benefits of mutation-targeted treatment in this group were mainly driven by the EGFR mutation and EGFR-TKI treatment." (PMID 39000058, 2024). "In lung adenocarcinoma with EGFR mutations, the EMT-related receptor tyrosine kinase AXL was positively correlated with PD-L1 expression." (PMID 38426097, 2024). "This is the first case report of severe megaloblastic anemia in a patient with advanced lung adenocarcinoma with an EGFR L858R mutation treated with erlotinib." (PMID 38448889, 2024). "Demographics and clinical characteristics of 272 patients in lung adenocarcinoma with EGFR mutation status." (PMID 38517388, 2024). "We are the first to report a case of EGFR-KDD mutated lung adenocarcinoma with concurrent brain metastasis treated with furmonertinib." (PMID 38974236, 2024). "Univariate analysis of EGFR mutation status in patients with lung adenocarcinoma with MPE [Mean ± SD, n (%)]." (PMID 37775991, 2024). "NCI-H1975 is a lung adenocarcinoma cell line with L858R and T790M EGFR mutations that are sensitive to Osimertinib, whereas PC9 cells have a Del19 EGFR mutation and are also sensitive to Osimertinib." (PMID 39231972, 2024). "Positive EGFR mutation is an independent risk factor for brain metastasis in patients with lung adenocarcinoma and has important clinical guiding significance." (PMID 38605303, 2024). "This case illustrates the potential limitations of osimertinib in treating bone metastasis in patients with EGFR-mutated lung adenocarcinoma." (PMID 39108772, 2024). "Polymerase chain reaction detected a mutation in EGFR (exon 21 L858R); therefore, the patient was diagnosed with stage IV lung adenocarcinoma harboring an EGFR mutation." (PMID 39246871, 2024). "Compared with standard chemotherapy, EGFR tyrosine kinase inhibitors (TKIs) generally obtain better tumor control in patients with EGFR-mutated lung adenocarcinoma." (PMID 38974236, 2024). "The EGFR ex19 Del and L858R mutations account for 90% of EGFR mutation-positive cases and affect approximately 50% of individuals with lung adenocarcinoma in the Asian population." (PMID 39619439, 2024). "This article summarizes the diagnosis and treatment of a patient with late-stage lung adenocarcinoma with Her-2 overexpression and EGFR mutation, aiming to explore the treatment efficacy of the antibody-drug conjugate (ADC) disitamab vedotin." (PMID 39726714, 2024). "The highest mutation rate in lung adenocarcinoma involves EGFR, reaching up to 20%, with an incidence rate of NSCLC in Asians between 40-60%, making EGFR a critical factor for NSCLC." (PMID 39575424, 2024). "Mutations in the epidermal growth factor receptor (EGFR) are a pivotal determinant in the etiology of lung adenocarcinoma (LUAD)." (PMID 39343971, 2024). "Among those identical DEGS, 32 common genes were identified between hypopharyngeal cancer and EGFR‐mutated lung adenocarcinoma through the Venny tool." (PMID 38783639, 2024). "EGFR-mutated lung adenocarcinoma patients with brain metastases typically experience shorter survival." (PMID 38515096, 2024). "Signs of paraneoplastic skin syndrome were observed, leading to a diagnosis of epidermal growth factor receptor mutation-positive lung adenocarcinoma (cT3N2M1c, stage IV, exon 19 del)." (PMID 39703278, 2024). "In the LUX-Lung 3 study, PFS of patients with EGFR-mutated advanced lung adenocarcinoma was longer with afatinib than with doublet chemotherapy (11.1 vs. 6.9 months; HR = 0.58, 95% CI = 0.43–0.78, p = 0.001)." (PMID 38194721, 2024).
lung adenocarcinoma (continued). "Many studies have indicated that the EGFR mutation rate was higher in lung adenocarcinoma patients, but different studies had different methods for further pathologic classification of adenocarcinoma." (PMID 39364008, 2024). "Gefitinib is one of the most extensively utilized epidermal growth factor receptor-tyrosine kinase inhibitors (EGFR-TKIs) for treating advanced lung adenocarcinoma (LUAD) patients harboring EGFR mutation." (PMID 38472205, 2024). "GSE212398 for hypopharyngeal cancer and GSE198672 for EGFR‐mutated lung adenocarcinoma datasets were used for the investigation." (PMID 38783639, 2024). "The third-generation EGFR-TKIs have significantly improved the efficacy and prognosis of patients with EGFR-mutated lung adenocarcinoma and brain metastases." (PMID 38515096, 2024). "Herein, we describe a rare case of megaloblastic anemia in a patient with lung adenocarcinoma harboring EGFR mutations after erlotinib treatment." (PMID 38448889, 2024). "Bronchoscopic biopsy results confirmed a diagnosis of lung adenocarcinoma and gene mutation analysis showed positive for EGFR exon 19 deletion." (PMID 38898314, 2024). "Approximately 15% of Caucasian patients and 30%-40% of Asian patients with lung adenocarcinoma carry EGFR mutations." (PMID 38298194, 2024). "According to the medical records, EGFR mutation-positive tumor was found only in one patient with lung adenocarcinoma (tumor sample ad2), whose tumor had a classical oncogenic mutation in the form of the exon 19 deletion in the EGFR gene in the cancer cells." (PMID 39199657, 2024). "In this study, we developed an MIL‐based deep learning model to analyze the prevalence of EGFR mutations in WSIs of patients with lung adenocarcinoma." (PMID 39358807, 2024). "EGFR kinase domain duplication (EGFR-KDD) is an infrequent oncogenic driver mutation in lung adenocarcinoma." (PMID 38974236, 2024). "EGFR mutations are more common in adenocarcinoma than in squamous carcinoma, and 51.4% of advanced lung adenocarcinoma patients in Asia have this mutation; the EGFR variation frequency is higher in women and nonsmoking patients." (PMID 38902753, 2024). "Initially diagnosed with lung adenocarcinoma, these patients underwent genetic testing that revealed EGFR mutations." (PMID 39227379, 2024). "A dangerous constituent of hypopharyngeal cancer is lung adenocarcinoma with EGFR mutation, which are reported to have some associations with each other." (PMID 38783639, 2024). "Recent findings from the ADAURA trial have shown that epidermal growth factor receptor tyrosine kinase inhibitors (EGFR-TKIs) significantly improve DFS duration by approximately 18 months in stage IB lung adenocarcinoma (LADC) patients with EGFR mutations." (PMID 39232762, 2024). "This study will contribute to identifying cohorts with an increased risk of postoperative recurrence, based on both the EGFR mutation and PD-L1 expression status, among patients with surgically resected lung adenocarcinoma." (PMID 39281386, 2024). "Transformation into SCLC represents a rare mechanism of resistance to EGFR-TKIs in advanced lung adenocarcinoma harboring EGFR mutations, accounting for approximately 5-15% of resistance etiologies." (PMID 39234244, 2024). "A TF‐gene network was contrived by 10 hub genes of hypopharyngeal cancer and EGFR‐mutated lung adenocarcinoma." (PMID 38783639, 2024). "The aim of this study was to investigate long-term outcomes in patients with EGFR mutated (EGFRmut) lung adenocarcinoma as well as the presence of LM." (PMID 39727929, 2024). "Unlocking genetic commonalities between hypopharyngeal cancer and EGFR‐mutated lung adenocarcinoma using bioinformatics analysis, we identified 10 key hub genes suggesting potential therapeutic molecules for both diseases." (PMID 38783639, 2024).
lung adenocarcinoma (continued). "Epidermal growth factor receptor tyrosine kinase inhibitors (EGFR-TKIs) have significant anticancer effects in advanced-stage lung adenocarcinoma with sensitive EGFR mutations such as exon 19 deletion or L858R mutation, with response rates of around 70~80%." (PMID 38786296, 2024). "EGFR mutations, a prevalent oncogenic driver in lung adenocarcinomas among the Caucasian population, occur in approximately 11–15% of cases and represent the most common targetable oncogenic addiction in the first-line setting." (PMID 39509381, 2024). "In our study, only one patient with recurrent EGFR-mutated lung adenocarcinoma received ICIs before EGFR-TKI therapy." (PMID 39281386, 2024). "Among them, the micropapillae structure is crucial for the promotion of tumor development, thus potentially determining the malignancy potential of EGFR-mutated lung adenocarcinomas." (PMID 38933439, 2024). "This study demonstrated the real‐world data about the combination of an EGFR TKI and an anti‐VEGF agent as the first‐line therapy for stage IV lung adenocarcinoma harboring susceptible EGFR mutation in Taiwan." (PMID 38523603, 2024). "This study aimed to assess the intrinsic impacts of the expression of PD-L1 on postoperative recurrence and the prognosis in patients with epidermal growth factor receptor (EGFR)-mutated lung adenocarcinomas." (PMID 39281386, 2024). "The patient, a 63-year-old female, initially presented with an EGFR exon 21 L858R mutated left lung adenocarcinoma in 2017, treated successfully with surgical resection and subsequent monitoring." (PMID 39193383, 2024). "In lung adenocarcinoma, EGFR mutations are more common among Asian, young, female, non or light smokers." (PMID 38347643, 2024). "Here, we report a 65-year-old female diagnosed with stage IIIC lung adenocarcinoma located in the right inferior lobe, harboring uncommon EGFR L858M/L861R mutations." (PMID 39679364, 2024). "The mutations of oncogenic epidermal growth factor receptor (EGFR) is an important cause of lung adenocarcinoma (LUAD) malignance." (PMID 39343971, 2024). "Inhibition of mutant EGFR in lung adenocarcinoma cells has been shown to cause increased expression of FGFR3, and inhibition of FGFR3 was shown to block the formation of drug-tolerant cells." (PMID 38473364, 2024). "Recent studies have shed light on the correlation between co-mutations and unfavorable outcomes, as well as the underlying mechanism that promotes resistance in EGFR-mutant lung adenocarcinoma." (PMID 39066920, 2024). "Based on the hub genes of patients with hypopharyngeal cancer and EGFR‐mutated lung adenocarcinoma who have these two diseases concurrently, certain therapeutic compounds are envisaged." (PMID 38783639, 2024). "The area under the curve (AUC) of pleural fluid CEA for the prediction of EGFR mutation in lung adenocarcinoma patients with MPE was 0.774, with a cut‐off value of 7.94 ng/mL, sensitivity of 87.76%, and specificity of 53.54% (P < 0.001)." (PMID 37775991, 2024). "It is well known that the incidence of EGFR mutations is higher in Asian patients with lung adenocarcinoma (LUAD), and the overall EGFR mutation prevalence in the mainland Chinese population is 50.2%." (PMID 38680859, 2024). "Epidermal growth factor receptor tyrosine kinase inhibitors (EGFR‐TKIs) are the first‐line treatment option for patients with advanced lung adenocarcinoma carrying EGFR mutations." (PMID 37775991, 2024). "The somatic mutation rate of the epidermal growth factor receptor (EGFR) gene is approximately 50% in Asian populations with lung adenocarcinoma and around 30% in Western populations." (PMID 39160638, 2024).
lung adenocarcinoma (continued). "Or should everyone with stage-2 lung adenocarcinoma with an exon 19 epidermal growth factor receptor (EGFR) mutation receive osimertinib after definitive surgery and chemotherapy or just those relapsing?" (PMID 38459165, 2024). "One hundred ninety-four EGFR-mutated lung adenocarcinoma patients with brain metastases who received third-generation EGFR-TKI treatment were included in this study from January 1, 2017 to March 1, 2023." (PMID 38515096, 2024). "NEOS is a prospective, multicenter, single-arm study designed to evaluate the efficacy and safety of osimertinib as a neoadjuvant treatment in resectable EGFR mutation (+) lung adenocarcinoma." (PMID 39081712, 2024). "There are individual case reports of lung adenocarcinoma patients with EGFR gene mutations transforming into small cell lung cancer pathology after treatment with tyrosine kinase inhibitors." (PMID 39114303, 2024). "A total of 194 EGFR-mutated lung adenocarcinoma patients with brain metastases receiving third-generation EGFR-TKI were enrolled in this study." (PMID 38515096, 2024). "The third-generation EGFR-TKI showed significant efficacy in EGFR-mutated lung adenocarcinoma patients with brain metastases, and the combined line plot of C + R can be utilized to predict short-term efficacy and iPFS." (PMID 38515096, 2024). "On the other hand, thyroid transcription factor 1 (TTF-1) is associated with EGFR mutations, while NapsinA is highly specific for lung adenocarcinoma." (PMID 38807858, 2024). "This study focused on analyzing postoperative recurrence and the prognosis in 221 consecutive patients with lung adenocarcinoma, considering both EGFR mutations and the PD-L1 expression status." (PMID 39281386, 2024). "Approximately, 25% of lung adenocarcinoma patients have targetable driver mutation including EGFR, ALK, ROS-1, BRAF, MET, and cErbB2." (PMID 38668879, 2024). "Except for CREB, the cAMP/PKA-regulated phosphoprotein DARPP-32 enhances ERBB3/EGFR heterodimerization and promotes EGFR inhibitor resistance in EGFR-mutated lung adenocarcinoma." (PMID 38233872, 2024). "Mutationsin epidermal growth factor receptor (EGFR) are found in approximately 48% of Asian and 19% of Western patients with lung adenocarcinoma (LUAD), leading to aggressive tumor growth." (PMID 38540317, 2024). "Afatinib emerges as a pivotal first-line treatment option for patients afflicted with lung adenocarcinoma, particularly those harboring complex EGFR mutations." (PMID 38754409, 2024). "In EGFR exon 20 insertion mutation of lung adenocarcinoma, amivantanab was registered for progression after platinum-based chemotherapy." (PMID 38605928, 2024). "A 70-year-old woman presented with chest tightness and dyspnea for 1 week and ventricular fibrillation upon admission, with a medical history of lung adenocarcinoma harboring an EGFR exon 21 p.L858R mutation." (PMID 39267801, 2024). "Epidermal growth factor receptor (EGFR) mutations are prevalent in approximately half of Asian patients diagnosed with lung adenocarcinoma." (PMID 39423210, 2024). "This is a long-term follow-up case report of a 71-year-old man with lung adenocarcinoma and choroidal metastasis harboring an epidermal growth factor receptor mutation." (PMID 39246871, 2024). "Multifactorial logistic regression analysis showed that EGFR mutation status was an independent risk factor for brain metastasis in lung adenocarcinoma patients (P = 0.001), and the difference was statistically significant." (PMID 38605303, 2024). "In this study, genotyping of resected tumor tissue from an elderly female patient diagnosed with lung adenocarcinoma reported the co-mutations of EGFR L858R/G719S and BRAF V600E." (PMID 39135785, 2024). "For instance, MIL‐based approaches have been applied to predict EGFR mutations in lung adenocarcinoma, genetic alterations in gastric cancer, and mutation status in breast carcinoma." (PMID 39358807, 2024).